ASIC2 (acid sensing ion channel subunit 2)
Description:
Forms pH-gated trimeric sodium channels that act as postsynaptic excitatory sensors in the nervous system. Upon extracellular acidification, these channels generate rapid, transient inward currents that fully desensitize. Highly selective for sodium, they are permeable to other cations. By forming heterotrimeric channels with ASIC1, could contribute to synaptic plasticity, learning, and memory. Additionally, as acid sensors at nerve terminals, plays a role in mechanosensation and phototransduction (By similarity).
Synonyms: BNC1; BNaC1; MDEG; ACCN; ACCN1; ASIC2a; hBNaC1
Tractability: Antibody: UniProt places it where antibodies can reach, with high confidence; its Gene Ontology location is reachable by antibodies, with high confidence; UniProt predicts a signal peptide or a membrane-spanning region.
Gene: Protein-coding gene on chromosome 17 (33,013,087 to 34,174,964, reverse strand). Ensembl gene ENSG00000108684.
Subcellular location: Cell membrane
Pathways (Reactome):
Transport of small molecules: Stimuli-sensing channels
Gene Ontology:
Molecular function: pH-gated sodium channel activity; protein binding; ligand-gated sodium channel activity; monoatomic cation channel activity; monoatomic ion channel activity; monoatomic ion-gated channel activity; sodium channel activity
Biological process: sensory perception of sour taste; sodium ion transmembrane transport; cellular response to acidic pH; cellular response to xenobiotic stimulus; regulation of postsynapse assembly; sodium ion transport
Cellular component: plasma membrane; dendritic spine; membrane; neuron projection; neuronal cell body; postsynaptic density membrane; synapse
Genetic constraint (gnomAD): Loss-of-function variants: 23 observed, 55.11 expected, observed/expected ratio (o/e) 0.42, 90% interval 0.3 to 0.59. The upper end of that interval is the gene's LOEUF score, 0.59, which puts it in group 2 of 6, group 1 being the genes least tolerant of losing a copy. Missense variants: 614 observed, 695.89 expected, observed/expected ratio (o/e) 0.88, 90% interval 0.82 to 0.94. Synonymous variants: 303 observed, 291.16 expected, observed/expected ratio (o/e) 1.04, 90% interval 0.95 to 1.14.
Homologues: Orthologues: chimpanzee ASIC2 (99% identical), macaque ASIC2 (99% identical), dog ASIC2 (99% identical), pig ASIC2 (99% identical), rat Asic2 (97% identical), guinea pig ASIC2 (84% identical), tropical clawed frog asic2 (75% identical), rabbit ASIC2 (72% identical), mouse Asic2 (71% identical), zebrafish asic2 (58% identical), Caenorhabditis elegans acd-2 (20% identical), Drosophila melanogaster ppk18 (19% identical), and 22 more. Paralogues in human: ASIC1 (55% identical), ASIC3 (43% identical), ASIC4 (39% identical), SCNN1B (22% identical), SCNN1A (21% identical), SCNN1G (21% identical), ASIC5 (20% identical), SCNN1D (20% identical).
Diseases named in the same sentence as ASIC2 in open-access papers:
ASIC2 is named in the same sentence as 71 diseases in open-access papers, as found by Europe PMC text mining. Sharing a sentence is not in itself a finding about the gene and the disease. The quoted sentences say what the papers report.
glioma (15 papers, 2008 to 2025). A benign or malignant brain and spinal cord tumor that arises from glial cells (astrocytes, oligodendrocytes, ependymal cells). "In both these cases, the molecular lesion that causes the ASIC2 trafficking defect is unknown – in glioma it might be oncogenic mutations or modifications, whereas, in vascular smooth muscle cells, the truncated form could be involved." (PMID 24609033, 2014). "For example, ASIC1 and ASIC2 levels are dramatically increased in glioma, and blockage of cation currents significantly delays the glioma growth metastasis." (PMID 41392978, 2025). "Inhibition of ASIC2 channels by recombinant analogs of Manbalkin-1 can control the carcinogenic process of leukemia, glioma and melanoma cells." (PMID 38505262, 2024). "This is confirmed by the fact that glioma proliferation and migration is inhibited by the ASIC1a inhibitor toxin, PcTx1, as well as ASIC2." (PMID 35207041, 2022). "Mixed tetrameric channels integrated by acid-sensing ion channel subunits (ASIC1 or ASIC2) together with subunits forming an epithelial sodium channel (ENaCα or ENaCγ) are thought to form the active ASIC channels at the glioma cell surface." (PMID 32392767, 2020). "ASIC2 knockdown aggravates acidosis-induced injury of rat C6 glioma cells, accompanied with increased intracellular Ca2+." (PMID 28927426, 2017). "ASIC2 channel expression is reduced in all glioma types compared to control samples." (PMID 38607019, 2024). "In further experiments, it was found that the increase in ASIC2 protein on the cell surface could reduce the proliferation and migration of glioma cells." (PMID 38505262, 2024). "Furthermore, expression levels of ASIC1 and ASIC2 correlate with the progression of low-grade gliomas to high-grade glioma; therefore, their inhibition decreases in vitro migration of glioma cells." (PMID 32575381, 2020). "Moreover, ASIC2 knockdown aggravates acidosis-induced injury of rat C6 glioma cells, accompanied with increased intracellular Ca2+, indicating the protective role of ASIC2 on glioma cells under acidosis by preventing calcium overload." (PMID 28927426, 2017). "This treatment to increase levels of PM ASIC2 also inhibited glioma cell migration." (PMID 24609033, 2014). "HSC70, but not HSP70, was found to associate with ASIC2 in glioma cells, and HSC70 knockdown increased the cell-surface expression of ASIC2 and reduced the channel activity." (PMID 24609033, 2014). "However, on the contrary, ASIC2 can inhibit the proliferation and migration of glioma cells." (PMID 38505262, 2024). "Interestingly, ASIC2 in astrocytes inhibits the growth of gliomas." (PMID 35207041, 2022). "In line with our in vitro results, ACCN1 (ASIC2) was downregulated in all types of glioma samples as compared to the non-tumour samples used as control (P < 0.001, two-sided t-test)." (PMID 29057936, 2017). "Only ASIC2 was mostly retained at the ER and associated with HSC70; glycerol, a non-specific chemical chaperone, increased total and PM ASIC2 levels, and inhibited cell migration, mimicking the glioma paradigm." (PMID 24609033, 2014). "It was shown in a study that ASIC2 is not expressed at the cell surface of high grade glioma (brain tumor) cells and this may be responsible for the constitutively activated inward Na+ current, which promotes increased cell growth and migration in these cells." (PMID 31481665, 2019). "Furthermore, although ASIC2a and ASIC3 are highly expressed in adenoid cystic carcinoma, surface expression of ASIC2 abolished the amiloride-sensitive inward Na+ current and promoted a reversion of a high-grade glioma cell to a more normal (i.e., nonmalignant) astrocytic phenotype." (PMID 27403419, 2016).
colorectal cancer (7 papers, 2017 to 2025). A primary or metastatic malignant neoplasm that affects the colon or rectum. "In accordance with our findings, ASIC1 and ASIC2 are upregulated in colorectal cancer cells subjected to acidosis." (PMID 32764426, 2020). "Acidic exposure led to up-regulation of the acid-sensing ion channel, ASIC2, in colorectal cancer (CRC) cells." (PMID 28927426, 2017). "Gene manipulation was applied to reveal the potential of ASIC2 on invasion, proliferation, colony formation of colorectal cancer (CRC)." (PMID 28927426, 2017). "Indeed, all these channels are involved in acidosis-induced tumor progression: ASIC1 and α-ENaC mediate the epithelial–mesenchymal transition of pancreatic cancer, while ASIC2 promotes the invasion and metastasis of colorectal cancer." (PMID 35837090, 2022). "The ASIC2 gene has been suggested to be involved in metastasis in triple-negative breast cancer and shown to promote metastasis in colorectal cancer through activation of the calcineurin/NFAT1 axis." (PMID 40564925, 2025).
epilepsy (7 papers, 2017 to 2025). A brain disorder characterized by episodes of abnormally increased neuronal discharge resulting in transient episodes of sensory or motor neurological dysfunction, or psychic dysfunction. "Neurons overexpressing ASIC2a fired more frequently than control neurons, suggesting the involvement of ASIC2 in the neuroexcitatory imbalances observed in epilepsy." (PMID 40548375, 2025). "The involvement of ASICs, including ASIC2, is observed in neuronal excitability, especially in relation to imbalances in neuronal excitation seen in seizure and epilepsy." (PMID 35207035, 2022).
multiple sclerosis (5 papers, 2007 to 2022). A progressive autoimmune disorder affecting the central nervous system resulting in demyelination. "Earlier, we described the genetic association, within the Nuoro population, between Multiple Sclerosis (MS) and rs28936, located in ASIC2 3′UTR." (PMID 30549327, 2019). "The SNP rs28936 located in the 3’ UTR of ASIC2 gene is significantly associated with Multiple Sclerosis (MS), an autoimmune disease that your immune system mistakenly attacks cells in the myelin and interrupts nerve signals from your brain to other parts of your body." (PMID 36451823, 2022).
glioblastoma (4 papers, 2013 to 2023). The most malignant astrocytic tumor (WHO grade IV). "By contrast, increasing surface expression of the ASIC2 subunit suppressed the proliferation and migration of glioblastoma cells." (PMID 29056828, 2017). "It has previously been reported that ASIC1 and ASIC2 are present in different cell lines derived from glioblastoma patients." (PMID 29057936, 2017). "ASIC1 and ASIC2 have effects on the growth and migration of glioblastoma cells." (PMID 24381558, 2013). "Amiloride- and PcTx1-sensitive cation currents in human glioblastoma are produced by mixed ASIC and ENaC components, including ASIC1 and ASIC2." (PMID 29056828, 2017).
Hepatic steatosis (3 papers, 2024 to 2025). Steatosis is a term used to denote lipid accumulation within hepatocytes. "Our lab has demonstrated that mice lacking normal levels of two degenerin ion channels, Acid-Sensing Ion Channel 2 (Asic2) and beta Epithelial Sodium Channel (βENaC), were protected from weight gain, loss of insulin sensitivity, and liver steatosis during high-fat diets." (PMID 41300348, 2025). "Additionally, loss of ASIC2 and βENaC confers a greater protection against the development of insulin resistance and hepatic steatosis in female mice as compared to male mice." (PMID 39224121, 2024). "Because our findings from Asic2 null mice are published elsewhere, the current study investigated the importance of βENaC in the pathogenesis of diet-induced obesity and hepatic steatosis." (PMID 41300348, 2025). "Our study provides a novel, yet unexpected, finding: loss of ASIC2 and βENaC leads to remarkable protection against HFD-induced weight gain, intrabdominal fat accumulation, hepatic steatosis, insulin resistance, and plasma lipid profile changes." (PMID 39224121, 2024). "In the current investigation, we provide evidence that male and female mice lacking normal levels of ASIC2 and βENaC are protected from metabolic dysfunction and hepatic steatosis associated with a high-fat diet." (PMID 39224121, 2024). "A previous study from our laboratory showed that mice lacking βENaC and Asic2 were protected from diet-induced obesity and hepatic steatosis." (PMID 41300348, 2025). "In a recently published investigation, we determined that Asic2-knockout mice show modest protection from high-fat diet-induced weight gain, but no protection from hepatic steatosis." (PMID 41300348, 2025). "We recently showed that mice lacking normal levels of Asic2 and βENaC were unexpectedly protected from weight gain, metabolic disruption, and hepatic steatosis when placed on a 10‐week 60% kcal high‐fat diet (HFD)." (PMID 40939131, 2025). "The intent of this study was to determine the contribution of βENaC to diet-induced obesity and hepatic steatosis phenotypes observed in mice lacking Asic2 and βENaC." (PMID 41300348, 2025). "We previously demonstrated that mice lacking normal levels of βENaC and ASIC2 are protected from diet-induced obesity, metabolic disruption, and hepatic steatosis." (PMID 41300348, 2025). "Asic2 is expressed in a greater percentage of hypothalamic neurons important in energy homeostasis, and Asic2 knockout mice show substantial differences in total and basal energy expenditure, motor activity, and food consumption patterns, but no protection from hepatic steatosis." (PMID 41300348, 2025).
neuroblastoma (3 papers, 2008 to 2022). Neuroblastoma (NB) is the most common solid, extracranial childhood tumor. "We also examined whether such membrane trafficking mechanisms of ASIC2 isoforms appear in SH-SY5Y cells, which are popularly used human neuroblastoma cells." (PMID 27477936, 2016).
bipolar disorder (2 papers, 2016 to 2019). A disorder of the brain that causes unusual shifts in mood, energy, activity levels and the ability to carry out day-to-day tasks. "ASIC2 was a computationally predicted interactor of the gene SMG6, structural variants in which have been associated with schizophrenia or bipolar disorder in a Spanish population." (PMID 31481665, 2019).
COVID-19 (2 papers, 2022). A disease caused by infection with severe acute respiratory syndrome coronavirus 2. "In our study, rs75953002 in the intron of ASIC2 was identified to be associated with NAbs level of COVID-19 vaccine immunization." (PMID 36451823, 2022). "After comparing the significant genes in T2D and COVID-19, five genes were found to be shared between T2D and COVID-19: PTPRD, CSMD1, MAGI1, ASIC2, DAB1." (PMID 36482905, 2022). "Further, in our gene-based analysis, five genes (DAB1, ASIC2, MAGI1, CSMD1 and PTPRD) were shared between T2D and COVID-19." (PMID 36482905, 2022).
Hypertension (2 papers, 2013 to 2014). The presence of chronic increased pressure in the systemic arterial system. "Conscious Asic2−/− mice showed hypertension, exaggerated sympathetic and decreased parasympathetic control of the circulation, and decreased gain of the baroreflex, which suggests a role for ASIC2 in determining mechanosensitivity of arterial baroreceptors." (PMID 23490035, 2013).
malignant melanoma (2 papers, 2021). "Only ASIC1 and ASIC2 were shown to be expressed in human melanoma and skin cancer tissues previously." (PMID 34680442, 2021). "In this study, we investigate the expressions of ASIC1, ASIC2, TRPV1 and TRPV4 in squamous cell carcinoma (SCC), basal cell carcinoma (BCC), malignant melanoma (MM) and in nevus cell nevi (NCN)." (PMID 34199609, 2021). "In this study, we investigated the expression profiles of ASIC1, ASIC2, TRPV1 and TRPV4 in malignant melanoma (MM), squamous cell carcinoma (SCC), basal cell carcinoma (BCC) and in nevus cell nevi (NCN)." (PMID 34199609, 2021).
metabolic syndrome (2 papers, 2024 to 2025). A cluster of metabolic risk factors for CARDIOVASCULAR DISEASES and TYPE 2 DIABETES MELLITUS. "ASIC2, primarily expressed in neurons, is related to cardiovascular function and has been linked to metabolic syndrome in mice." (PMID 40502754, 2025). "These novel findings suggest that loss of ASIC2 and βENaC offer a significant protection against HFD-induced metabolic syndrome." (PMID 39224121, 2024). "Our findings indicate that the degenerin proteins ASIC2 and βENaC are involved in the progression of metabolic syndrome." (PMID 39224121, 2024). "The CNS signaling pathway of feeding–satiety–energy expenditure could also play a role in protecting ASIC2-/-/βENaCm/m mice from HFD-induced metabolic syndrome." (PMID 39224121, 2024). "What evidence suggests that ASIC2 or βENaC might contribute to the metabolic syndrome and obesity?" (PMID 39224121, 2024). "The potential importance of degenerin proteins ASIC2/βENaC in the development of metabolic syndrome has not been previously explored." (PMID 39224121, 2024). "It is possible that PPARα may inhibit the activity of a degenerin channel, possibly ASIC2 or a hybrid ENaC–ASIC channel, that has yet to be identified in hepatic cells, and disruption of this regulatory system in the liver may be a driver for metabolic syndrome development." (PMID 39224121, 2024).
nephrotic syndrome (2 papers, 2021 to 2023). A collection of symptoms that include severe edema, proteinuria, and hypoalbuminemia; it is indicative of renal dysfunction. "al. recently demonstrated that a novel splice variant of ASIC2 is amiloride sensitive and contributes to Na+ retention in a rodent model of nephrotic syndrome, a phenomenon that was previously considered to be largely mediated by ENaC." (PMID 37707951, 2023). "Moderate proteolysis of ASIC2 may also activate it, as previously reported for ENaC and plasmin, the excretion of which is increased during nephrotic syndrome." (PMID 34166227, 2021). "This further supports the notion that acid pH is probably not the unique activating factor of ASIC2 in ASDN during nephrotic syndrome." (PMID 34166227, 2021).
skin cancer (2 papers, 2021). "In our study, we investigated the expressions of ASIC1, ASIC2, TRPV1 and TRPV4 in common skin tumors, namely SCC, BCC, NCN and MM." (PMID 34199609, 2021). "In conclusion, ASIC1, ASIC2, TRPV1 and TRPV4 are expressed by most common skin tumors." (PMID 34199609, 2021). "ASIC1, ASIC2, TRPV1 and TRPV4 in skin tumors might be involved in tumor progression, thus being potential diagnostic and therapeutic targets." (PMID 34199609, 2021).
adenoma (1 paper, 2024). A neoplasm arising from the epithelium. "Our results showed that, whether in the samples of cancer, adenoma or paracancer, the top three MP-RNA counted by partner numbers were coding for ASIC2, GPD1L and FAM213A, indicating that these three RNAs were always active in both normal and abnormal colon tissues." (PMID 38773399, 2024).
Anxiety (1 paper, 2018). Intense feelings of nervousness, tension, or panic often arise in response to interpersonal stresses. "Of notice, genes associated to differentially methylated clusters included the acid sensing ion channel subunit 2 (Asic2) gene, relevant to both acidification detection and anxiety, and Neuregulin 3 (Nrg3) gene, associated with “neurogenesis”, “cell motility” terms." (PMID 29396481, 2018).
Arthritis (1 paper, 2022). Inflammation of a joint. "In neurodegenerative diseases in which there are issues of inflammation such as IVDD and arthritis and antibiotic-induced hearing loss, more evidence identifying ASIC2’s relevant function is needed before interventions can realistically be endeavored." (PMID 35207035, 2022). "Future studies should determine whether ASIC2 is directly involved in arthritis and IVDD." (PMID 35207035, 2022). "Similar to the neurodegenerative evidence, investigations into IVDD and arthritis have not specified ASIC2 as having a bigger role than ASIC1a." (PMID 35207035, 2022).
diabetic neuropathy (1 paper, 2021). A chronic, pathological complication associated with diabetes mellitus, where nerve damages are incurred due to diabetic microvascular injury involving small blood vessels that supply these nerves, resulting in peripheral and/or autonomic nerve dysfunction. "We used immunohistochemistry associated with a battery of antibodies to identify the axon and Schwann related cells (since both are involved in diabetic neuropathy) and a series of putative mechanoproteins (PIEZO2, ASIC2 and TRPV4) which are involved in mechanotransduction." (PMID 34640627, 2021).
disc degeneration (1 paper, 2019). "ASIC2 was the most frequently expressed in human intervertebral disc cells compared with other ASICs and participated in disc degeneration." (PMID 31531354, 2019).
Hip dysplasia (1 paper, 2024). The presence of developmental dysplasia of the hip. "However, micro‐CT images of hip joints from Asic2 KO mice and control littermates showed similar morphologies and no signs of hip dysplasia, suggesting that loss of Asic2 does not affect hip joint morphology." (PMID 36951012, 2024). "Therefore, we analysed the hip joints of Asic2 KO mice for features of hip dysplasia." (PMID 36951012, 2024).